CAV1 (caveolin 1)
Diseases named in the same sentence as CAV1 in open-access papers (continued):
Sharing a sentence is not in itself a finding about the gene and the disease.
neurodegenerative disease (20 papers, 2008 to 2023). A disorder of the central nervous system characterized by gradual and progressive loss of neural tissue and neurologic function. "It is extensively recognized that cav-1 is closely associated with the pathophysiological processes and risk factors of neurodegenerative diseases." (PMID 38102662, 2023). "Earlier, we summarized a comprehensive overview about how cav-1 modulates pathogeneses of neurodegenerative diseases." (PMID 38102662, 2023). "Our work builds upon previous observations that CAV1 function is neuroprotective in neurodegenerative disease and in ALS in particular." (PMID 33264630, 2020). "Cav-1 is believed to be a biomarker in neurodegenerative diseases and take an active part in memory and learning." (PMID 31514313, 2019). "Besides caveolin-1, caveolin-2 has been also found to facilitate leukocyte infiltration in brain ECs, contributing to the development of common neurodegenerative diseases." (PMID 38067108, 2023). "Beyond the role of caveolin-1, some studies have shown that caveolin-2 may play roles in neurodegenerative diseases, particularly AD." (PMID 38067108, 2023). "Due to the important role of Cav1 in cholesterol transport and homeostasis, findings suggest that altered cholesterol homeostasis may affect Cav1 expression and the pathogenesis of several neurodegenerative diseases." (PMID 36854997, 2023). "For example, gene therapy to enhance Cav-1 expression in cortical neurons has been proposed to alleviate other forms of neurodegenerative disease, it is thus possible that similar approaches may have a resultant neuroprotective effect in the eye." (PMID 34819834, 2021). "Loss or reduction of cav-1 expression in a mouse model of HD suppresses the motor phenotype, suggesting that cav-1 is a critical factor for neurodegeneration and could be a novel therapeutic target for many neurodegenerative diseases including PD." (PMID 26627850, 2015). "Also, neurological abnormalities in caveolin-1 knockout mice and a link between caveolin-1 gene haplotypes and neurodegenerative diseases have been reported." (PMID 25324780, 2014). "Seven genes were observed to be involved in both infections of three coronaviruses and two neurodegenerative diseases, including the HSP90AA1, ALDH2, CAV1, COMT, MTOR, IGF2R and HSPA1A." (PMID 37015947, 2023). "We also investigated the trafficking of CB1R and CAV1 in response to MCD treatment, in the light of its potential relevance for the regulation of apoptosis and neurodegenerative diseases." (PMID 17714745, 2008).
adenocarcinoma (14 papers, 2014 to 2025). A common cancer characterized by the presence of malignant glandular cells. "In NSCLC, CAV1 overexpression has been associated with higher disease stage and inferior survival in patients with adenocarcinoma, but a robust correction of the survival data for stage and treatment was not done in these studies." (PMID 25222296, 2014). "Thus, loss of CAV1 significantly reduced the migration of both adenocarcinoma cell lines in the absence or presence of 4β-TPA." (PMID 26054531, 2015). "Analysis of the differential expression of Cav1 by histotype revealed that all of the positive primary adenocarcinomas (7 cases) maintained Cav1 expression at the brain metastatic site and that 7 out of 31 acquired Cav1 expression during metastasis (chi-square test p < 0.001)." (PMID 26315660, 2015). "Studies conducted in A549 human adenocarcinoma cells showed that CAV1 expression was upregulated after incubation with Paclitaxel, suggesting that continuous exposure to Paclitaxel can lead to a drug-resistant phenotype at least in part through upregulation of CAV1." (PMID 35158857, 2022). "(A) CAV1 levels in small-cell (ECC4) and adenocarcinoma (TGBC) cell lines from intestine." (PMID 39960760, 2025).
breast (11 papers, 2007 to 2022). "Analyzing these results in relation to the different histotypes, 22 of 74 (29.7%) lung AC, and 6 of 38 (15.8%) lung SCC showed up-regulated cav-1 mRNA expression and the difference by statistical analysis was significant (P=0.041)." (PMID 22200856, 2012). "Furthermore, in mouse chronic liver injury studies, MCAM is enriched in hepatocyte derived proliferative ducts, over those derived from mature BECs alongside AHSG, ALB, CAV1 and RBP48." (PMID 31350390, 2019).
kidney diseases (9 papers, 2015 to 2025). "Here, we focus on some chemical compounds, drugs, and various extracts from traditional Chinese medicine, which target Cav-1 or its associated signaling pathway and summarize their application in kidney diseases." (PMID 34955837, 2021). "Given that caveolin-1/CAV1 and caveolae have been proposed to influence signaling, transport and disease processes in the kidney it is important to understand the mechanisms that underlie induction of caveolin-1/CAV1 and potentially other caveolar proteins in kidney disease." (PMID 29065889, 2017). "CAV1 emerges as a potential target for regulating cellular metabolism in the treatment of kidney diseases." (PMID 40013149, 2025). "It has been found that miR-204 and circAKT1 affect the progression of kidney disease by regulating Cav-1." (PMID 34955837, 2021). "It has been reported that Cav-1 plays a key role in regulating the RhoA/Rock pathway, which is involved in inflammation and apoptosis in kidney disease." (PMID 34955837, 2021). "Although based on a small group of cases for each condition, this pilot IHC analysis confirmed the reliability of focal and diffuse Cav-1 positivity (Grade II-III) to specifically detect antibody-mediated rejection injury in a wide range of kidney diseases." (PMID 34680435, 2021). "Increased cav-1 expression has been observed in several fibrotic kidney diseases in both animal models and humans." (PMID 30995923, 2019). "On the basis of the function of Cav-1 in regulating lipid metabolism, catalpol may play a key role in kidney disease by regulating the expression of Cav-1." (PMID 34955837, 2021). "As renal transplantation is suggested as an in vivo model of accelerated tissue fibrosis, genotyping of CAV1 may be relevant in other renal and non-renal diseases characterized by tissue fibrosis." (PMID 25945124, 2015). "Because Cav-1 plays an important role in cellular metabolism and activities related to cellular life, especially the development of various kidney diseases, recent studies targeting Cav-1 for the treatment of various diseases, especially kidney diseases, have become a research hotspot." (PMID 34955837, 2021). "To support the reliability of Cav-1 in the setting of c-ABMR, we evaluated its IHC expression in an exploratory series of additional transplant kidney diseases." (PMID 34680435, 2021). "Furthermore, the mechanism by which Cav-1 regulates cellular metabolism and participates in the pathophysiology of kidney diseases has not been completely elucidated." (PMID 34955837, 2021). "However, the mechanism by which Cav-1 regulates cellular metabolism and kidney disease is not clearly understood." (PMID 34955837, 2021). "The repressive effect of H2O2, especially on caveolin-2/CAV2, PTRF/CAVIN1 and SDPR/CAVIN2 protein levels and the lack of effect on caveolin-1/CAV1 protein, argued against a major role of oxidative stress in induction of caveolar proteins in kidney disease." (PMID 29065889, 2017).
neurological disorders (8 papers, 2010 to 2025). "Inhibiting high-voltage-activated calcium channels (HVACCs; CaV1/CaV2) is therapeutic for myriad cardiovascular and neurological diseases." (PMID 31403402, 2019). "In module-5, VCP shown interaction with 5 proteins (AKTI, CAV1, HSPA8, DNM1L, TKT) functionally associated with enzyme binding processes and most of these genes are mostly related to neoplasms disorder followed by nervous system diseases." (PMID 34918006, 2022). "Because Cav-1 phosphorylation is essential for SynCav1-promoted axonal growth in early-stage of differentiation, disruption or imbalances in P-Cav-1 may have implications for neurological diseases or during aberrant neuronal development." (PMID 31379509, 2019).
inflammation (7 papers, 2014 to 2022). Aberrant reaction of the microcirculation characterized by movement of fluid and leukocytes from the blood into extravascular tissues. "Next, CAV1 is a gene involved in diverse signalling pathways and plays an essential role in cell proliferation, apoptosis, lipid migration, and exhibits a protective role in intestinal inflammation for IBD." (PMID 35543875, 2022).
bacterial infection (6 papers, 2010 to 2023). "This is in concordance with results reporting that senescent cells had increased levels of caveolin-1, associated with higher rates of bacterial infection." (PMID 34936648, 2021). "Regarding the increased susceptibility of both patients to bacterial infections, it is noteworthy that caveolae have been found on stimulated B-lymphocytes (plasma cells) and that murine Cav1-/- B-lymphocytes showed reduced in vitro IgG3-secretion after LPS-stimulation." (PMID 20300641, 2010). "This study promotes future research to develop drugs by targeting the specific motif of cav-1 or TLRs against bacterial infection and macrophage-mediated inflammation." (PMID 36817491, 2023). "Specifically, TLR9 constitutively associates with Cav-1 and facilitates MyD88-mediated TRAF3 and IRF3 signal transduction, providing the observed InP effect in fatal doses of bacterial infection." (PMID 31534550, 2019). "Cav-1 plays an important role in the immune response against bacterial infection." (PMID 33558888, 2021). "Additionally, different subsets of leukocytes derived from CAV1-null mice have been analyzed in terms of response to either parasitic or bacterial infection." (PMID 30246033, 2018).
colon (5 papers, 2019 to 2022). "Further studies with larger samples are needed for confirming the relationship between CAV1 (rs7804372) gene polymorphism and digestive system tumors." (PMID 34128850, 2021). "CAV-1 plays an important role in cell migration and is a regulator of the K-RAS oncogene in colon carcinogenesis." (PMID 31889941, 2019).
heart disease (5 papers, 2012 to 2022). "It has been extensively reported that caveolin 1 impacts on oxidative stress and cardiac disease by controlling eNOS activity." (PMID 33374685, 2020). "Interestingly, mice null for caveolin-3 and caveolin-1 develop severe heart disease, while caveolin-3 over expression induces a Duchenne-like phenotype in mice." (PMID 25914646, 2015). "Although high levels of serum HDLC lowers the risk of heart disease, there is still no direct evidence that CaV1 is involved in HDLC metabolism." (PMID 24278029, 2013). "In particular, caveolin-1 (Cav-1) and caveolin-3 (Cav-3) have been identified as potential regulators of vascular dysfunction and heart disease and might even confer cardiac protection in certain settings." (PMID 22934034, 2012).
respiratory disease (5 papers, 2011 to 2025). "A subset of genes co-expressed with AQP4 and associated to respiratory disease were assigned to potential anti-tumorigenic function like CAV1, EDNRB, or SELENBP1, whereas genes more related to pro-tumorigenic function like CDK2, FOXM1, PLK1 or RRM1 were found to be anti-correlated with AQP4." (PMID 21548930, 2011). "Therefore, the CAV1 protein loss can cause a variety of respiratory diseases." (PMID 35069688, 2021). "Taken together, Cav-1 and autophagy play an important regulatory role in a variety of respiratory diseases and are expected to be potential targets for future treatment." (PMID 41030451, 2025).
endocrine diseases (3 papers, 2016 to 2025). "In the gene group of endocrine system disorder, the most important gene was thyroid peroxidase (TPO), this gene was overexpressed, and the next genes carbonic anhydrase VI (CA6), caveolin protein 1 (CAV1), and solute carrier family type 12 (SLLC12A3) were underexpressed." (PMID 35059043, 2022).
immune diseases (3 papers, 2014 to 2024). "We thus presume that the upregulated DEGs such as Cav1, CD200R1, TNFRSF17 and CXCR3 and downregulated DEGs such as EIF1AY and DDX3Y in healthy female may be involved in gender predominance of some immune diseases." (PMID 24741625, 2014). "Moreover, the upregulated DEGs (Cav1, CD200R1, TNFRSF17, and CXCR3) and downregulated DEGs (EIF1AY and DDX3Y) in healthy female may be involved in gender predominance of some immune diseases." (PMID 24741625, 2014).
psychiatric disorder (3 papers, 2017 to 2022). A disorder characterized by behavioral and/or psychological abnormalities, often accompanied by physical symptoms. "For these reasons, we propose that Shank effects on Cav1 currents and CREB target expression could play an important role in the pathophysiology of ASD (and potentially other psychiatric disorders)." (PMID 28477407, 2017).
vasculopathy (3 papers, 2010 to 2025). "In summary, caveolin-1 is one of the important mediators between vasculopathy and fibrosis." (PMID 37762589, 2023). "However, the exact connection of the differential expression of caveolin-1 in ECs and pericytes with vasculopathy and fibrosis needs to be further investigated." (PMID 37762589, 2023). "Furthermore, the expression of both RNF213 and Cav-1 in endothelial cells, the primary cell type implicated in RNF213-related vasculopathies, further implies that their interaction may be of biological significance." (PMID 40497951, 2025). "As a first step in determining the possible interactions between RNF213 and Cav-1, we analyzed their subcellular localizations in endothelial cells, which express both RNF213 and Cav-1, and which are considered as the primary targets of RNF213-related vasculopathies." (PMID 40497951, 2025).
brain diseases (2 papers, 2022 to 2024). "Because glia depletion is major cause of synaptic abnormalities and brain disorders, this finding suggested a possible role of glial depletion in the fetal brain in the premature aging and neurodegeneration in Cav1-null mice." (PMID 38334607, 2024).
peripheral neuropathy (2 papers, 2024 to 2025). A disorder affecting the peripheral nervous system. "All the results showed that the protective effect of DAPT on nab-PTX-induced peripheral neuropathy was related to inhibition of the Notch/HMGB1/caveolin-1 pathway." (PMID 40291503, 2025). "DAPT relieved nab-PTX-induced peripheral neuropathy by inhibiting the activation of the HMGB1/caveolin-1 signaling pathways and decreasing the levels of inflammatory cytokines and oxidative stress in vivo and in vitro." (PMID 40291503, 2025).
central nervous diseases (1 paper, 2022). "Previous investigations have demonstrated that Cav‐1 is associated with several central nervous diseases." (PMID 36054154, 2022).
gynecological tumors (1 paper, 2019). "Herein, further investigations are needed to study the role of Cav-1 in the carcinogenesis of gynecological tumors." (PMID 31759347, 2019). "In other words, higher expression of Cav-1 contributes to the incidence and development of gynecological tumor." (PMID 31759347, 2019). "Although the role of Cav-1 has been reported in many kinds of tumors, there are a few reports about the role of Cav-1 in gynecological tumors." (PMID 31759347, 2019). "This review summarizes some mechanisms of Cav-1 in the development and progression of gynecological tumors." (PMID 31759347, 2019). "Therefore, this review summarized some mechanisms and functions of Cav-1 in the development and progression of gynecological tumors." (PMID 31759347, 2019). "Therefore, the up-regulation of Cav-1 expression by gene therapy may significantly inhibit some gynecological tumors progression." (PMID 31759347, 2019).
infectious disease (1 paper, 2021). A disorder directly resulting from the presence and activity of a microbial, viral, or parasitic agent in humans. "Furthermore, Src and caveolin 1 (CAV1) could be potentially valuable targets for the control of infectious diseases." (PMID 33966642, 2021).
reproductive diseases (1 paper, 2025). "Cav-1 and autophagy have also been found to be associated with reproductive system diseases." (PMID 41030451, 2025).
retinopathy (1 paper, 2021). "Indeed, caveolin-1 siRNA inhibition reduced retinal neovascularization in a murine model of oxygen-induced retinopathy but worsened choroidal and retinal neovascularization in Cav-1-deficient mice." (PMID 35054437, 2021).
skin disorder (1 paper, 2022). Any deviation from the normal structure or function of the skin or subcutaneous tissue that is manifested by a characteristic set of symptoms and signs. "The expression of CAV-1 in skin disorders has been investigated using several techniques." (PMID 36532050, 2022).
CAV1 also shares sentences with these, for which no sentence is quoted: bladder transitional cell carcinoma (5 papers); nasopharyngeal carcinoma (5); alveolar rhabdomyosarcoma (4); colon adenocarcinoma (4); viral myocarditis (4); alcoholic fatty liver disease (3); cardiac arrhythmias (3); caveolinopathies (3); cystic fibrosis (3); dementia (3); Glucose intolerance (3); multiple sclerosis (3); myopathy (3); papillary carcinoma of the thyroid (3); Abdominal obesity (2); alcohol (2); autism spectrum disorder (2); benign ovarian tumors (2); cardiac interstitial fibrosis (2); chronic pancreatitis (2); colorectal adenocarcinoma (2); congenital generalized lipodystrophy type 4 (2); congenital heart defect (2); cutaneous melanoma (2); familial partial lipodystrophy (2); gall bladder cancer (2); Hereditary breast cancer (2); left ventricular hypertrophy (2); Lewis lung carcinoma (2); lipoma (2).
A further 157 diseases each share a sentence with CAV1 in 2 papers or fewer.